PRMT5 (protein arginine methyltransferase 5)
Diseases named in the same sentence as PRMT5 in open-access papers (continued):
Sharing a sentence is not in itself a finding about the gene and the disease.
lung carcinoma (continued). "This suggests that PRMT5 is a promising target for lung cancer treatment; however, the pharmacology of PRMT5 inhibition and its effects on immune cells are largely unknown." (PMID 35111150, 2021). "Additionally, the down-regulation of PRMT5 prevents cell proliferation at the G1 phase in human lung cancer." (PMID 33495409, 2021). "We evaluated the effect of a PRMT5-specific inhibitor in human and mouse lung cancer cell lines." (PMID 35111150, 2021). "Here, it is shown that PRMT5 promotes lung cancer cell proliferation through the Smad7‐STAT3 axis." (PMID 34026434, 2021). "Similar results were observed in another lung carcinoma cell line H358, suggesting that PRMT5 might potentiate STAT3 activation induced by autocrine IL‐6 in lung carcinoma cells." (PMID 34026434, 2021). "Overall, our findings address an unmet clinical need through the combination of PRMT5 inhibition and anti-PD-L1 therapy, which may represent a promising strategy for lung cancer therapy." (PMID 35111150, 2021). "The findings in this study showed that PRMT5 was overexpressed in human lung cancer cells." (PMID 30461193, 2019). "In lung cancer, PRMT5 could specifically catalyze the symmetrical dimethylation of histone H4R3 in the promoter regions of miR-99 family members, leading to increased growth and metastasis of lung cancer cells." (PMID 30922330, 2019). "Furthermore, we generated PRMT5 stable knockdown cell lines (A549 and H1299 cells) and explored the functions of PRMT5 in lung cancer cell proliferation." (PMID 30461193, 2019). "Our findings also suggest that targeting PRMT5 may have therapeutic potential for treatment of human lung cancer." (PMID 30461193, 2019). "Additionally, PRMT5 promoted lung cancer cell proliferation through direct interaction with Akt and regulation of Akt activity, but not interaction with PTEN and mTOR." (PMID 30461193, 2019). "Here, we showed that PRMT5 was highly expressed in human lung cancer cells and lung cancer tissues." (PMID 30461193, 2019). "Down‐regulation or inhibition of PRMT5 markedly reduced Akt phosphorylation at Thr308 and Ser473, whereas the expression of PTEN and mTOR phosphorylation was unchanged, indicating that PRMT5 was an important upstream regulator of Akt and induced lung cancer cell proliferation." (PMID 30461193, 2019). "Coincidently, we also knocked down PRMT5 expression using siRNA in lung cancer cells." (PMID 30736843, 2019). "Moreover, we uncovered that PRMT5 promoted lung cancer cell proliferation via regulation of Akt activation." (PMID 30461193, 2019). "Finally, we evaluated the PRMT5 expression level and Akt activity in human lung cancer tissues and adjacent normal tissues." (PMID 30461193, 2019). "shRNA was then used to independently knock down PRMT5 in these lung cancer cell lines." (PMID 28903384, 2017). "Collectively, identified compounds are powerful probes that could be used to understand more about the biologic roles of PRMT5 and potentially assist in defining a therapeutic strategy for lung cancer treatment." (PMID 28806746, 2017). "PRMT5 and p44 are re-expressed in lung cancer and are required for lung tumor growth." (PMID 27480244, 2016). "In searching for genes that mediate PRMT5 and WDR77 functions in lung cancer cells, we performed DNA microarray analysis (GSE56757) with lung adenocarcinoma A549 cells expressing WDR77 or PRMT5 shRNA and found that the loss of WDR77 or PRMT5 expression significantly up-regulated GLIPR1 expression." (PMID 26988096, 2016). "Expression of PRMT5/p44 is ubiquitous in lung cancer and hyperplasia." (PMID 27480244, 2016). "More important, PRMT5 and WDR77 were re-activated in lung cancers and the small hairpin RNA (shRNA)-mediated silencing of PRMT5 or WDR77 expression strongly inhibited growth of lung cancer cells in the tissue culture and abolished growth of lung tumor xenografts in the nude mouse." (PMID 26988096, 2016).
lung carcinoma (continued). "Indeed, PRMT5 over-expression can influence progression of leukemia, lymphoma, glioma, breast, prostate and lung cancer." (PMID 24098663, 2013). "Since only limited data is available regarding the role PRMT5 in lung cancer, the goal of this study was to evaluate a large set of NSCLC and pulmonary neuroendocrine tumors (NET) for PRMT5 expression and the potential correlation of expression with clinicopathological variables." (PMID 24326178, 2013). "Additionally, PRMT5 inhibition can suppress tumour growth of lung cancer cells in mice." (PMID 38760429, 2024). "Targeting FOXP3 by the PRMT5 inhibitor could be promising in lung cancer treatment." (PMID 38898200, 2024). "We investigated whether GSK591, a specific inhibitor of PRMT5, could control KLF5 expression and proliferation in lung cancer cells, as PRMT5 has emerged as a promising therapeutic target for cancer treatment, and several specific small‐molecule inhibitors of PRMT5 have been developed." (PMID 37461162, 2023). "Interestingly, in our previous report, we demonstrated that PRMT6 asymmetrically dimethylates the R9 and R372 sites of ENO1 in lung cancer, which is different from our finding in this study that PRMT5 only symmetrically dimethylates the R9 site of ENO1 in ovarian cancer." (PMID 36999124, 2023). "However, knockdown of PRMT5 promoted the proliferation of lung cancer cells." (PMID 36999124, 2023). "Taken together, our findings indicate that abnormal expression of PRMT5 is closely related to the lung tumor stages and survival rates in patients with lung cancer, and PRMT5 may regulate angiogenesis, metastasis, and EMT through HIF-1α and PI3K/Akt signaling pathway." (PMID 37400960, 2023). "Additionally, inhibiting or silencing PRMT5 also suppressed EMT markers in lung cancer cells." (PMID 37400960, 2023). "Additionally, a growing number of clinical investigations have proven that EPZ015666 can exhibit antitumor properties by inactivating PRMT5 in acute myeloid leukemia, lung cancer, and retinoblastoma, and is a novel and potential therapeutic target independent of the SAM binding site." (PMID 36364261, 2022). "In addition, PRMT5 expression correlated with the epithelial–mesenchymal transition in lung cancer cell lines and the subcellular localization of PRMT5 varied depending on the histologic grade of lung adenocarcinoma suggesting PRMT5 as a marker of prognostic value." (PMID 34200178, 2021). "Additionally, PRMT5 could promote human lung cancer cell proliferation through direct interaction with AKT and regulation of AKT activity." (PMID 34124017, 2021). "For example, PRMT5 could regulate human lung cancer cell growth via targeting Akt signaling." (PMID 34124017, 2021). "Additionally, we also detected the expression of LSH and PRMT5 at the protein level in lung cancer specimens, identifying that both of them were overexpressed in carcinoma tissue relative to adjacent normal tissue, and their protein levels displayed a positive relationship as well." (PMID 32994405, 2020). "Importantly, the KM-PLOT database revealed that lung cancer patients with higher expression of either LSH or PRMT5 may have poorer survival." (PMID 32994405, 2020). "However, it is still unclear whether PRMT5 interacts with Akt, another important oncoprotein in human cancers, and regulates Akt activity in human lung cancer." (PMID 30461193, 2019). "As an oncogene, PRMT5 serves critical functions in several cellular responses, including the development, progression, and aggressiveness of cancer, and has been studied in multiple tumour types, including leukaemia, lymphoma, lung cancer, liver cancer, colorectal cancer and breast cancer." (PMID 29679004, 2018).
lung carcinoma (continued). "Since PRMT5 is also required for mediating the molecular consequences of EMT, these observations strongly suggested that SHARPIN is essential for maintaining PRMT5-associated chromatin environments in lung cancer A549 cells, with the activation of expression of cancer metastasis-related genes." (PMID 28903384, 2017). "However, the heterogeneity in ErbB2/3 and FGFR3 expression was observed in lung cancer cells, suggesting regulation of their expression by PRMT5/p44 may be lost in some cancer cells and their functions may be redundant in cancer cell growth." (PMID 27480244, 2016). "Thus, PRMT5 and p44 are required for lung cancer cell proliferation." (PMID 27480244, 2016). "It has been shown in cell culture and in animal models that PRMT5 is an important epigenetic modifier of histone and non-histone proteins in lymphomas, breast, colorectal and lung cancer, and its overexpression is associated with aggressive phenotype in these models." (PMID 24326178, 2013). "In the present study, we found that PRMT5-mediated methylation is important for constitutive activation of STAT3, as well as for CSC maintenance and tumorigenesis in lung cancer cells." (PMID 38760429, 2024). "On the other hand, PRMT5, as a key oncogenic regulator, promotes the EMT process in human lung cancer cells through the EGFR/AKT signaling axis, thereby exacerbating resistance development." (PMID 38525426, 2024). "As shown in the survival plot the overexpressed PRMT5 and FXR1 (SD > 1) alone or in combination, lead to poor patient survival in HNSCC and lung cancer patients." (PMID 38709899, 2024). "PRMT5 methylates the oncogenic factor Krüppel-like factor 5 (KLF5) to prevent its degradation, thereby promoting the maintenance and proliferation of lung cancer cells." (PMID 38418849, 2024). "Further studies are needed to fully understand the mechanism by which PRMT5 regulates angiogenesis and EMT and its potential as a therapeutic target in lung cancer treatment." (PMID 37400960, 2023). "Further investigation showed that PRMT5 directly interacted with and methylated KLF5 in human lung cancer cells." (PMID 37461162, 2023). "In summary, PRMT5 methylates KLF5 to prevent its degradation, thereby promoting the maintenance and proliferation of lung cancer cells." (PMID 37461162, 2023). "Collectively, our findings suggest that PRMT5 methylates KLF5 at arginine 41 to stabilize KLF5 and promote lung cancer cell growth." (PMID 37461162, 2023). "Altogether, our findings indicate that PRMT5 directly interacts with and methylates KLF5 in human lung cancer cells." (PMID 37461162, 2023). "However, the function of PRMT5 in angiogenesis and lung cancer EMT is still largely unknown." (PMID 37400960, 2023). "To explore the potential function of HIF-1α and PRMT5 in lung cancer, we first evaluated the mRNA expression of HIF-1α in PRMT5 depletion cells." (PMID 37400960, 2023). "To confirm our findings, we assessed the mRNA and protein expression levels of PRMT5 and KLF5 in lung cancer cell lines and normal human foetal lung fibroblast cells (IMR90)." (PMID 37461162, 2023). "In the present study, we found that both PRMT5 and KLF5 were highly expressed and closely correlated in lung cancer cells." (PMID 37461162, 2023). "Consistent with our previous results, we observed significantly higher expression of both PRMT5 and KLF5 in lung cancer cell lines compared to IMR90." (PMID 37461162, 2023). "In this study, we uncovered that PRMT5 functions as an arginine methyltransferase for KLF5 on arginine 41, leading to increased stability of the KLF5 protein in lung cancer." (PMID 37461162, 2023). "Protein arginine methyltransferase 5 (PRMT5) is considered as an oncogene known to be involved in different types of carcinomas, including lung cancer." (PMID 37461162, 2023).
lung carcinoma (continued). "We then assessed the tumour proliferation signature in lung cancer and found that both KLF5 and PRMT5 were positively correlated with tumour proliferation signature, suggesting a potential relationship between these two genes." (PMID 37461162, 2023). "In this study, we found that PRMT5 stabilizes KLF5, further increasing its expression in lung cancer cells." (PMID 37461162, 2023). "Inhibition of PRMT5 can inhibit the phosphorylation of protein kinase AKT1, thereby affecting the growth cycle of lung cancer cells." (PMID 35531958, 2022). "On the other hand, PRMT5 has been shown to activate the AKT1 and ERK signaling pathways by modifying histone H4R3, thereby promoting metastasis of lung cancer cells." (PMID 35531958, 2022). "The data showed that knockdown of PRMT5 in NCI-H460 cells decreased survival compared with the control group, suggesting that PRMT5 directly affects lung cancer line survival." (PMID 35111150, 2021). "The role of protein arginine methyltransferase 5 (PRMT5) in Janus kinase (JAK)‐signal transducer and activator of transcription 3 (STAT3) signaling pathway and lung cancer cell proliferation is unveiled." (PMID 34026434, 2021). "Depletion or inhibition of PRMT5 dramatically dampens STAT3 activation and thus suppresses the proliferation of human lung cancer cells." (PMID 34026434, 2021). "Homozygous deletion of the MTAP gene is frequently (~ 40%) seen in lung cancer patients, and leads to elevated levels of MTA, a metabolite known to act as an endogenous inhibitor of PRMT5 activity." (PMID 33691794, 2021). "Depletion or inhibition of PRMT5 dramatically dampens STAT3 activation and suppresses proliferation and migration of human lung cancer cells." (PMID 34026434, 2021). "Overexpressed PRMT5 promotes EMT by activating EGFR/AKT/β-catenin signaling in pancreatic cancer cells, as well as lung cancer cells." (PMID 34513846, 2021). "The findings position PRMT5 as a critical regulator of STAT3 activation, and suggest it as a potential therapeutic target for the treatment of human lung cancer." (PMID 34026434, 2021). "Collectively, our data solidly showed that MYOCD recruited PRMT5/MEP50 methyltransferase complex and epigenetically modified TGFBR2 promoter region to silence its transcription in lung cancer cells." (PMID 33995678, 2021). "To further explore the role of PRMT5 in lung cancer, we performed RNA sequence analysis on NCI-H460 cells that were stably transfected with PRMT5 shRNA and control shRNA using three biological replicates." (PMID 35111150, 2021). "Stable depletion of PRMT5 profoundly reduced endogenous STAT3 phosphorylation and expression of two STAT3 targets, e.g., survivin and c‐Myc, in lung carcinoma A549 cells." (PMID 34026434, 2021). "In this study, we aim to explore the effect of the combination of PRMT5 inhibitor (AMI-1) and cisplatin on cell viability in an in vitro lung cancer model, compared with normal bronchial epithelial cells." (PMID 34200178, 2021). "In A549 cells, Cav-1 and protein arginine methyltransferase 5 (PRMT5) can synergistically facilitate the exteriorization of Eno-1, a glycolytic enzyme that can promote lung cancer cell migration." (PMID 31991790, 2020). "To further investigate the role of PRMT5 in lung cancer cell proliferation, we used PRTM5 specific inhibitor, GSK591, to black PRMT5 activity and cell proliferation was evaluated." (PMID 30461193, 2019). "Although PRMT5 and p44 are ubiquitously expressed in all cancer cells, we observed heterogeneous expression of ErbB2, ErbB3, and FGFR3 in lung cancer cells and of some PRMT5/p44-target genes in various cancer cell lines in response to p44 silencing." (PMID 27480244, 2016). "JNJ, a potent PRMT5 inhibitor currently in clinical trials, notably for non-Hodgkin lymphoma and lung cancer, was evaluated in this study." (PMID 42123761, 2026).
lung carcinoma (continued). "Additionally, in LU99 lung cancer xenograft models, MRTX1719 exhibited dose-dependent tumor growth inhibition and nearly complete inhibition of PRMT5 activity at well-tolerated doses." (PMID 39826691, 2025). "We found that PRMT1 and PRMT5 expression, along with MEP50 the obligate cofactor of PRMT5, are generally higher in multiple sarcoma types, including EWSR1::FLI1 and EWSR1::ERG fusion-positive ES tumours, than in breast and lung cancer." (PMID 40823091, 2025). "Kaplan–Meier survival analysis did not reveal a statistically significant association between PRMT5 expression levels (high vs. low) and overall survival in either ADC or SCC lung cancer patients." (PMID 41301499, 2025). "As a result, we investigated whether silencing PRMT5 and PRMT1 affected FXR1, FXR2 and FMRP levels in oral and lung cancer cells." (PMID 38709899, 2024). "We wonder if the expression of PRMT5 and HIF-1α was changed in lung cancer cells induced by CoCl2." (PMID 37400960, 2023). "Importantly, PRMT5‐mediated KLF5 stabilisation induced the expression of target genes such as cyclin D1, slug and FGF‐BP1, which facilitated lung cancer cell proliferation and EMT." (PMID 37461162, 2023). "Here, we show that the expression levels of PRMT5 and KLF5 are highly expressed lung cancer." (PMID 37461162, 2023). "Targeting PRMT5/KLF5 and its downstream signalling pathways may represent a promising therapeutic strategy for lung cancer treatment." (PMID 37461162, 2023). "Collectively, these results suggest that PRMT5 is engaged in NO production and angiogenesis, which may lead to EMT and metastasis during lung cancer progression." (PMID 37400960, 2023). "Taking together, PRMT5 and PRMT6 may regulate tumor progression through different mechanisms in ovarian cancer and lung cancer, respectively." (PMID 36999124, 2023). "PRMT5 coordinates invasive phenotypes by methylating H3R2me1 for transcriptional activation and H4R3me2s for transcriptional repression, leading to FGFR3 pathway activation and TGFβ‐induced EMT in lung cancer cells." (PMID 35766227, 2022). "PRMT5 exhibits FGFR3-dependent regulation through the activation of AKT, ERK, and mTOR, and the activated FGFR signaling pathway plays an important role in promoting lung cancer cell proliferation." (PMID 36364261, 2022). "PRMT5 overexpression is involved in cell proliferation and survival in DLBCL and mantle cell lymphoma (MCL), as well as a variety of solid tumors including glioblastoma, lung carcinoma, melanoma, hepatocellular carcinoma (HCC), and colorectal cancer." (PMID 33989303, 2021). "Moreover, we knocked down PRMT5 expression in another human lung cancer line, HCC827, and the LLC mouse lung cancer cell line to further verify the function of PRMT5." (PMID 35111150, 2021). "Targeting PRMT5 reduced this inhibitory effect and promoted CD274 expression in lung cancer." (PMID 35111150, 2021). "Moreover, the protein arginine methyltransferase 5 (PRMT5) forms complex with the methylosome protein 50 (MEP50) to catalyze histone mono- and dimethylation of important EMT genes in lung cancer cells." (PMID 33803458, 2021). "In our study, we identified that LSH may serve as a substrate for the arginine methyltransferase PRMT5, and LSH methylation catalyzed by PRMT5 plays significant roles in regulating LSH activity to maintain lung cancer stem cell properties." (PMID 32994405, 2020). "Collectively, these results demonstrate that PRMT5 directly interact with Akt but no PTEN or mTOR in human lung cancer cells." (PMID 30461193, 2019). "This is not surprising given that PRMT5 over-expression has recently been identified in lung carcinoma, glioblastoma, B-cell lymphoma, mantle cell lymphoma, and melanoma, to name just a few." (PMID 26729154, 2015). "We also show that the PRMT5 protein expression is significantly increased in lung cancer but not in nonneoplastic alveolar and bronchial epithelium cell lines." (PMID 24326178, 2013).